IDH1 (isocitrate dehydrogenase (NADP(+)) 1)
Diseases named in the same sentence as IDH1 in open-access papers (continued):
Sharing a sentence is not in itself a finding about the gene and the disease.
glioma (continued). "Another study demonstrated that glioma cells with heterozygous IDH1 R132H mutation change TAMs towards a phagocytic anti-tumor phenotype." (PMID 37274252, 2023). "The archetype of these mutations is an arginine-to-histidine substitution in IDH1 (R132H) present in roughly 90% of IDH-mutant gliomas." (PMID 37049661, 2023). "Complete 1p/19q co-deletion, MGMT promoter methylation and IDH1 mutation which are associated with favorable outcomes in gliomas were more obvious in the low-risk group as risk scores increased (all p < 0.001, Spearman correlation)." (PMID 38057821, 2023). "αKC can also be synthesized by IDH, mutations in IDH1 are often detected in grade II or III gliomas." (PMID 38139462, 2023). "Conversely, the overexpression of glutamate dehydrogenase 2 (GLUD2) rescues the growth-inhibitory effect of IDH1 mutation in murine glioma progenitor cells." (PMID 37108511, 2023). "Another frequently mutated gene in gliomas (generally low grade) is isocitrate dehydrogenase 1 (IDH1), a key enzyme that regulates tryptophan metabolism." (PMID 36594466, 2023). "Although differences in TME have been described as potential contributors to different biological behavior in IDH1/2 mutated gliomas, current knowledge on TME composition in these glioma subtypes has yet to be enriched." (PMID 36831383, 2023). "Another ongoing clinical trial is being conducted on IDH1 or IDH2 mutation-bearing adult glioma patients to test if nivolumab (anti- PD-1 antibody) stops tumor growth and provides long-lasting control of the tumor." (PMID 37274252, 2023). "Isocitrate dehydrogenase 1 (IDH1) mutations and loss of 1p/19q or co-deletion of both are prognostically significant in glioma patients." (PMID 37697240, 2023). "The maximum MEG3 expression was observed in Grade 3 tumours indicating the contribution of IDH1 mutations since IDH1 mutant gliomas are the most frequently observed among all the grades of glioma tumours." (PMID 37525401, 2023). "In the past few years, predictive or prognostic evaluation of glioma has included IDH1/2 mutation, 1p/19q codeletion, and MGMT promoter methylation." (PMID 36991494, 2023). "The prevalence of IDH1 mutation predicts the origin of low-grade gliomas, as most of them have this mutation; on the contrary, primary glioblastomas have a low frequency of the mutated IDH1 gene." (PMID 36986469, 2023). "It is found to be mutated in low grade gliomas, while the wildtype IDH1 protein is mostly associated with primary GBM." (PMID 37046685, 2023). "As adult-type gliomas commonly harbor IDH1 (and less commonly, IDH2) mutations, testing the efficacy of IDH inhibitors in these tumors has become a research focus in recent years." (PMID 37781183, 2023). "The R132H isocitrate dehydrogenase one (IDH1) mutation is a prognostic biomarker present in a subset of gliomas and is associated with heightened survival when paired with aggressive surgical resection." (PMID 37733671, 2023). "A significant correlation was found between most members of the HDAC family and glioma grade, IDH1 mutation, and 1p/19q co-deletion." (PMID 37370767, 2023). "The PFS and especially the OS were not reached by all patients because of the low malignant course of especially IDH1 mutated gliomas." (PMID 37043120, 2023). "The most advanced clinical trial design is a phase 3, multicentre, randomised, double-blind, placebo-controlled study of AG-881 in subjects with residual or recurrent grade 2 glioma with an IDH1 or IDH2 mutation." (PMID 37296846, 2023). "From these findings, we conclude that the heterogeneity of TAMs relates to genetic alterations (e.g., NF1, PTEN, and IDH1 deletion and/or mutation) of glioma cells." (PMID 36594466, 2023).
glioma (continued). "To examine the impact of IDH1 mutation and activity on age-dependent glioma outcomes, we implanted GL26 transfected with either wild-type IDH1 or IDH1R132H into young and old syngeneic C57BL/6 (B6) mice." (PMID 37161052, 2023). "IDH1-mutant gliomas showed relatively lower IIS risk scores than IDH1-wild gliomas, which is consistent with the favorable prognosis of IDH1 mutant gliomas with reduced immune infiltration." (PMID 37543576, 2023). "More clinical trials are ongoing for monotherapies or combination therapies of mIDH1/2 inhibitors LY3410738 and IDH305 for gliomas and other solid tumors with IDH1/2 mutations (ClinicalTrials.gov)." (PMID 37546420, 2023). "Roughly 70% of grade 2–3 gliomas harbor mutations in either IDH1 or its mitochondrial counterpart IDH2." (PMID 36765553, 2023). "With the increase in risk score, the survival rate of glioma patients significantly decreased, consistent with the results that HIC2 and IDH1 mutations were protective factors, while age and grade were risk factors in glioma." (PMID 36650953, 2023). "The histological finding of “a diffusely infiltrating glioma” and the molecular finding of an IDH1/2 hotspot mutation are essential for classifying both astrocytoma and oligodendroglioma." (PMID 36717507, 2023). "Applying high-resolution semi-contact AFM mapping on an extended number of cells, we analyzed the nanomechanical properties of glioma early-passage cell cultures with a different IDH1 R132H mutation status." (PMID 36835465, 2023). "Gain-of-function mutations in IDH1/2 are the only known genomic alterations shared between the two PM glioma subtypes and represent one of the founder events for all PM tumors." (PMID 37055795, 2023). "As a 1p/19q codeletion, MGMT promoter methylation and IDH1 mutation is an important marker for the prognostic evaluation of glioma patients, and we investigated expression of HIC2 and this clinicopathologic feature." (PMID 36650953, 2023). "About 70-80% of lower-grade glioma and most secondary glioblastoma cases are associated with mutations in the IDH1 and IDH2 genes." (PMID 37546420, 2023). "Mutations in IDH1, as a tumor suppressor in human glioma cells through the negative regulation of Wnt/β-catenin signaling, improves survival conditions." (PMID 36900401, 2023). "A significant proportion of lower-grade glioma as well as many other types of human cancers are associated with neomorphic mutations in IDH1/2 genes (mIDH1/2)." (PMID 37546420, 2023). "Hotspot mutations of isocitrate dehydrogenase type 1 (IDH1) are an early and defining event in the development of a subgroup of gliomas." (PMID 37880243, 2023). "Tumor-associated IDH1 mutations confer the novel ability to produce the oncometabolite, 2-hydroxyglutarate (2HG), but also impair anti-tumor immunity in gliomas." (PMID 37161052, 2023). "For example, in our tested grade 4 gliomas, IDH1 mutation status, the well-known prognostic factor, predicted patient survival at an average c-index of 57% (95% CI, 47–67%) in the testing data sets." (PMID 37580817, 2023). "Phase 1 showed that twice daily oral administration resulted in anti-tumour activity in patients with recurrent/progressive IDH1-mutated glioma." (PMID 37296846, 2023). "The IDH1-vac is a peptide vaccine designed for the most common isocitrate dehydrogenase 1 (IDH1) mutation encoding IDH1R132H in gliomas." (PMID 36986491, 2023). "Secondary GBMs that developed from prior low-grade gliomas (both grades II and II) with mutant IDH1/2 were associated with decreased tumor aggressiveness." (PMID 38201528, 2023). "Noteworthy that isocitrate dehydrogenase 1 (IDH1) mutation status is one of the most effective prognostic markers for VTE in glioma." (PMID 37280670, 2023).
glioma (continued). "Various specific molecular alterations have recently been identified in gliomas; these include 1p/19q codeletion, IDH1 mutations, and O6-methylguanine-deoxyribonucleic acid methyltransferase promoter methylation." (PMID 37301546, 2023). "By examining the IDH1 mutation in glioma cells, researchers have discovered that this mutation results in increased succinylation of mitochondrial proteins." (PMID 37175631, 2023). "IDH1/2 hotspot mutations are well known to drive oncogenic mutations in gliomas and are well-defined in the WHO 2021 classification of central nervous system tumors." (PMID 37118755, 2023). "Glioma patients with IDH1 and IDH2 mutations present a better outcome than patients with IDH wild‐type." (PMID 37031458, 2023). "We now find that the IDH1 R132H mutation also disrupts the formation of PML-NBs in pediatric gliomas." (PMID 38066546, 2023). "We found that Isocitrate Dehydrogenase-1 (IDH1), which is commonly mutated in gliomas, enhances glioma vaccine efficacy in mice and discerns long from short survivors after vaccine therapy in GBM patients." (PMID 37161052, 2023). "1p19q codeletion is a combination of loss of the short arm chromosome 1 (1p) and the long arm of chromosome 19 (19q), 1p19q codeletion, MGMT promoter methylation and/or IDH1 mutation signified a better prognosis for glioma patients." (PMID 37864127, 2023). "In the latest classification standard of central nervous system (CNS) tumours by the WHO in 2021, invasive glioma was clinically classified according to IDH1/2 mutations." (PMID 37108242, 2023). "•Combination of clinical factors and radiomic features to construct models for predicting IDH1 gene mutations in glioma." (PMID 37354775, 2023). "The frequent IDH1 R132H mutation, in particular, can be readily detected, offering significant insights into glioma pathogenesis." (PMID 38137148, 2023). "Hotspot point mutations in IDH1/2 occur in the vast majority of adult low-grade gliomas representing a potential therapeutic target since IDH mutation is an early oncogenetic event, stable overtime, whose molecular downstream pathway is well known." (PMID 38273856, 2023). "Machine learning has also shown promise in the automated interpretation of histopathology of central nervous system tumors, identification of IDH1 mutation, MGMT promoter methylation, and 1p19q codeletion." (PMID 36836877, 2023). "IDH1/IDH2 mutations are also commonly found in high-grade gliomas and IDH1 inhibition prolonged disease control with favorable safety profile in a phase 1 clinical study." (PMID 35216478, 2022). "Compared to lower grade gliomas with IDH1 mutation and non-1p/19q codeletion (IDH1-Mut-noncodel, LGG), TMEM158 mRNA expression was higher in lower grade gliomas with IDH1 mutation and 1p/19q codeletion (IDH1-Mut-codel, LGG)." (PMID 34992215, 2022). "We analysed DNA from FFPE tumor samples of 58 glioma patients for mutations involving codon 132 of IDH1 or codon 172 of IDH2." (PMID 35361262, 2022). "The IDH1R132H mutation in glioma results in the neoenzymatic function of IDH1, leading to the production of the oncometabolite 2-hydroxyglutarate (2-HG), alterations in energy metabolism and changes in the cellular redox household." (PMID 35628596, 2022). "The expression of miR-181a was significantly lower in tumors of grade III and IV and was associated with IDH1 wild-type gliomas and a worse prognosis of patient overall survival." (PMID 36232448, 2022). "The aim of the study was to evaluate the relationship between tumor blood flow (TBF) measured by the pseudo-continuous arterial spin labeling (PCASL) method and IDH1 mutation status of gliomas as well as Ki-67 proliferative index." (PMID 35741254, 2022).
glioma (continued). "Beyond small molecule inhibitors, recently, it was reported the development of a new vaccine against gliomas carrying IDH1 mutation." (PMID 35804976, 2022). "One of the most exciting and clinically relevant observations was the discovery that a high percentage of glioma and a very small percentage of primary glioblastoma harbor mutations in the isocitrate dehydrogenase 1 (IDH1) gene." (PMID 36556190, 2022). "We thus suggest the use of pro-angiogenic and/or pro-hypoxic miRNAs as tools for monitoring patients specifically with IDH1/2-mutated gliomas." (PMID 35682718, 2022). "IDH1/2 mutation can cause some low-grade gliomas and secondary GBs, which indicates that certain low-tumorigenic mutations can cause gliomas with a relative slower evolution tendency." (PMID 35747806, 2022). "IDH1 mutations have been identified in many types of cancer, including glioma, colon cancer, leukemia, and prostate cancer." (PMID 35600114, 2022). "One of the most common genetic lesions in gliomas is a heterozygous mutation in IDH1, which occurs in 70–80% of grade II or III gliomas and most secondary glioblastomas." (PMID 36159801, 2022). "IDH1/2 mutations were found in 71% of conventional chondrosarcomas and 57% of dedifferentiated chondrosarcomas, as well as in gliomas and acute myeloid leukemia, suggesting a potential role for aberrant IDH function in the pathogenesis of these malignancies." (PMID 35198082, 2022). "We focused on the specific altered genes in TCGA, such as IDH1 (The most common mutation in glioma) and CIC (specific-mutation in low PSscore group), which had significantly low PSscore compared to wild type." (PMID 35274175, 2022). "IDH1-R132H catalyzes the formation of 2-hydroxyglutarate, which leads to epigenetic reprogramming of the glioma transcriptome and is associated with a better prognosis in glioma." (PMID 36276147, 2022). "For example, the anti-tumor effect of TMZ with ATMi or PARPi is enhanced in IDH1 mutant gliomas, and TMZ increases ATRi sensitivity in MGMT-deficient GB cells." (PMID 35406593, 2022). "These mutations, however, are not decisive for the development of epilepsy, as IDH1 and IDH2 mutations do increase the risk of developing seizures in gliomas, while LEATs typically lack IDH1 or IDH2 mutations and 1p/19q co-deletions." (PMID 36289737, 2022). "We recommend evaluating the IDH1/2 mutational status between the primary and secondary tumors when the primary tumor was glioma." (PMID 35505351, 2022). "In this preclinical multiparametric and multi-tracer PET study, the IDH1 mutation is associated with lower glioma uptake of [18F]DPA-714 in vitro, in vivo and ex vivo." (PMID 35303961, 2022). "Accumulating data indicates that enhancer of zeste homology 2 (EZH2) and isocitrate dehydrogenase 1 (IDH1) are implicated in promoting tumourigenesis in a myriad of malignancies including gliomas." (PMID 36292072, 2022). "Numerous studies have shown that IDH1 mutations lead to better overall survival in glioma patients and a better response to therapies." (PMID 36226186, 2022). "Gliomas with mutations in the isocitrate dehydrogenase 1 (IDH1) gene and the 1p/19q co-deletion have a better prognosis." (PMID 36291099, 2022). "Initial studies using methylation data from the Illumina GoldenGate array had characterized CIMP in glioma tumors, which was associated with both glioma histological subtype and IDH1/IDH2 mutations." (PMID 36360312, 2022). "Further multi-omics integrative analysis revealed a strong correlation between tumor immunosuppressive environment/IDH1 mutation and signature, suggesting that their cooperation plays an important role in glioma progression." (PMID 35601497, 2022).
glioma (continued). "IDH1 is a reliable diagnostic and prognostic marker for identifying low-grade gliomas and distinguishing between secondary and primary GBM." (PMID 35769466, 2022). "Other studies have found that BCAT1 expression was associated with aggressiveness and poor prognosis in IDH1 wild-type gliomas using MR imaging features." (PMID 36119495, 2022). "This metabolite was recently reported as a magnetic resonance spectroscopy (MRS) marker for the noninvasive detection of 1p/19q codeleted gliomas — e.g., oligodendroglioma (which, per definition, harbor IDH1 mutations)." (PMID 34941573, 2022). "The presence of IDH1/2 mutation is the major molecular diagnostic criterion for the classification of gliomas." (PMID 36613601, 2022). "The IDH1 mutation is more prevalent in low-grade gliomas and causes the formation of 2-hydroxyglutarate instead of alfa-ketoglutarate." (PMID 35737309, 2022). "Their orthotopic syngeneic glioma model demonstrated that IDH1 R132H mutation suppressed the STAT1 protein expression via 2-HG, thus decreasing the type 1-associated chemokines such as CXCL10 and affecting CD8+ T cell aggregation." (PMID 35769466, 2022). "Among them, there were 39% IDH1 mutations in the high-risk group and 91% in the low-risk group, which is consistent with previous reports that IDH1 wild-type gliomas tend to have a significantly worse prognosis." (PMID 35769464, 2022). "In 2016, the World Health Organization (WHO) classification of gliomas used molecular parameters including isocitrate dehydrogenase 1 and 2 (IDH1 and IDH2) mutations and 1p/19q codeletion status in addition to histopathological criteria." (PMID 35615996, 2022). "In this study, gliomas with low ALKBH5 expression showed higher proportion (66%) of IDH1 mutations compared to those with high ALKBH5 expression (21%)." (PMID 35444654, 2022). "The IDH1 R132H is among the most common mutations in glioma that serves as an important diagnostic and prognostic marker in patients." (PMID 35884887, 2022). "In particular, the statuses of isocitrate dehydrogenase 1 mutation (IDH1) and 1p19q codeletion are two crucial indicators in determining the genetic profiles of gliomas." (PMID 35053475, 2022). "In the present study, 13 patients (72.2%) had WHO grade 2 gliomas, and 3 patients (16.7%) had WHO grade 3 gliomas with IDH1 mutation, which progress slowly." (PMID 36347905, 2022). "As one of the most common mutations in glioma cells, the R132H variant of IDH1 occurs in 80%–90% of grade II and III gliomas." (PMID 36246611, 2022). "In an in vivo model was demonstrated that mutant IDH1 glioma, which is less aggressive than the wild-type IDH1 glioma, has low tumor TAN infiltration, and it is associated with the down-regulation of genes involved in chemotaxis." (PMID 35269652, 2022). "Accumulating studies have confirmed that IDH1 mutations are associated with the occurrence and development of glioma, and IDH1 mutations are more common in low grade glioma than in LGG." (PMID 35309512, 2022). "The content of reduced glutathione in the tumor tissues of patients with gliomas and the IDH1 mutation was significantly higher than in the wild-type IDH1 group." (PMID 36289655, 2022). "An increasing number of reports have shown that gliomas patients with IDH1 mutations have a better prognosis than the one with wild-type IDH1." (PMID 36245971, 2022). "IDH1mut is associated with a favorable response to chemotherapy and radiation, and 70–90% of low-grade-glioma and secondary glioblastoma present mutations in IDH1." (PMID 34687436, 2022). "Specifically, the IDH1 mutation R132H is found in secondary low-grade gliomas, and peptide vaccines targeting this mutation are currently in phase I clinical trials." (PMID 35203636, 2022). "Previous studies reported that an IDH1/2 mutation was associated with a better prognosis in patients with glioma, acute myeloid leukaemia or iCCA." (PMID 34905094, 2022).